BCL2 (BCL2 apoptosis regulator)
Diseases named in the same sentence as BCL2 in open-access papers (continued):
Sharing a sentence is not in itself a finding about the gene and the disease.
lymphoma (continued). "The anti-apoptotic factor Bcl-2 was previously identified as a key mediator of apoptosis because its overexpression in a murine lymphoma cell line protected cells from GC-induced apoptosis." (PMID 23658782, 2013). "The broad-acting protein kinase staurosporine was especially effective in overcoming GC resistance in mouse lymphomas that overexpressed Notch-1, Bcl-2, and/or Bcl-XL." (PMID 23431463, 2013). "We tested the sensitivity of selected lines with elevated Bcl-2 expression to BH3-mimetic ABT-199, and used U937 lymphoma cells with reduced Bcl-2 expression as a comparison." (PMID 24177192, 2013). "First, in the submandibular lymph node, neoplastic follicles with aberrant expression of BCL2 were present amongst the high-grade lymphoma infiltration." (PMID 21736761, 2011). "It has also been reported that TSA induced apoptosis in lymphoma cells by decreasing Bcl-2 expression significantly." (PMID 21687737, 2011). "We have shown that ApoG2 blocks binding of Bcl-2 and Bim and induces apoptosis in lymphoma cell lines with minimal toxicity." (PMID 21760983, 2011). "The block of apoptosis is a distinctive feature of the parental RLS tumor: a sixfold increase in the expression level of bcl-2 mRNA was observed for the parental RLS lymphosarcoma as compared with RLS40 tumor." (PMID 20470373, 2010). "Constitutive activation of NF-κB in lymphoma and consequent activation of downstream molecules like cIAP2, p21, and Bcl-2 increases the threshold for apoptosis." (PMID 20809973, 2010). "ABT-737, a small-molecule inhibitor of Bcl-2, Bcl-xl and Bcl-w, has demonstrated efficacy in several forms of leukemia, lymphoma as well as solid tumors." (PMID 19684859, 2009). "Several studies have reported the presence of leukemia-lymphoma-associated fusion genes (e.g., BCR/ABL1, IGH/BCL2, TCRβ/γ) in normal individuals." (PMID 21637673, 2009). "Consistent with previous reports, lymphomas were infrequently detected in p27 +/−, p27 −/−, or Lck-Bcl-2 transgenic mice during this time period." (PMID 18382684, 2008). "In this case, a lymphoma patient with overexpressed Bcl2 would be better served with romidepsin than with a hydroxamate hdaci." (PMID 19008999, 2008). "Histologically the lymphomas in p27 −/− Lck-Bcl-2 mice are lymphoblastic and frequently involve multiple organs suggesting an aggressive phenotype." (PMID 18382684, 2008). "Its tumorigenic potential has been demonstrated in animal models and is supported by the finding of over-expression of BCL2 in a variety of tumours and in lymphomas in which BCL2 acts as an oncogene." (PMID 18510726, 2008). "Bcl-2-expressing U937 lymphoma cells were coincubated with purified NKT cells from each normal donor." (PMID 17311012, 2007). "NKT cells derived from three normal donors all showed markedly increased cytotoxicity against Bcl-2-positive U937 lymphoma cells when combined with the HA14-1 small-molecule inhibitor of Bcl-2." (PMID 17311012, 2007). "Bcl-2 expression was detected in all lymphoma specimen before therapy, albeit only with a low to moderate intensity." (PMID 17473827, 2007). "We evaluated this in U937 lymphoma cells, and A02 melanoma cells, which both show strong Bcl-2 expression." (PMID 17311012, 2007). "Antisense oligonucleotides targeting bcl-2 have been used to reduce the expression of bcl-2 in phase 1 clinical trials with lymphomas." (PMID 15928664, 2005). "In epithelial tumours the mechanisms leading to bcl-2 protein expression are certainly different from lymphomas." (PMID 12454767, 2002). "Bcl-2 positive lymphomas are characterised by very high levels of bcl-2 protein in 100% of tumour cells, which is related to specific translocations." (PMID 12454767, 2002).
lymphoma (continued). "PCR is a rapid and easy technique that can detect the abnormal rearrangement of the bcl-2 gene and clonal IgH rearrangement, indicating the presence of lymphoma." (PMID 1419624, 1992). "Small molecule targeted drugs and CAR-T cell therapy, represented by BTK inhibitors and Bcl-2 inhibitors have achieved breakthrough results in the treatment of lymphoma, but they still face restrictions such as limited single-drug efficacy, drug-resistant recurrence, and toxic reactions." (PMID 41993181, 2026). "Specifically, we observed a significant decrease in the expression of anti-apoptotic genes Bcl-XL and Bcl-2 in lymphoma cells treated with eimbinostat, which may partially account for the observed induction of apoptosis." (PMID 40284412, 2025). "In contrast, lymphomas with dual MYC and BCL6 rearrangements represent a more diverse group and have variable gene expression profiles and mutational spectra, making them markedly different from DLBCL/HGBL-MYC/BCL2." (PMID 40126346, 2025). "Moreover, this efficacy extended to cell lines derived from a mouse model developing lymphoma as a result of oncogenic B-cell specific expression of Myd88L252P and BCL2, which mimic the constitutive NF-κB activation observed in ABC-type DLBCL." (PMID 41173858, 2025). "Fluorescence in situ hybridization (FISH) is a cornerstone diagnostic tool in lymphoma, serving as the gold standard for detecting specific gene rearrangements, including MYC, BCL2, and BCL6, as well as gene fusions such as IGH::MYC and IGH::BCL2." (PMID 41010038, 2025). "Therefore, in the 5th WHO classification, these lymphoma cases have been excluded from the DLBCL/HGBL-MYC/BCL2 grouping and are now reclassified as a subtype of DLBCL, NOS, or HGBL, NOS according their cytomorphology and followed by genetic aberrations." (PMID 40126346, 2025). "In addition, Bcl-2 expression was higher in CD20+ tumor cells (a lymphoma feature) than in CD68+ macrophages." (PMID 41415285, 2025). "Bcl-2 dysregulation is seen in several illnesses, such as lymphomas and epilepsy." (PMID 40540445, 2025). "Similarly, in previous studies, positive BCL2 expression has been associated with an increased risk of recurrence, poor treatment response, and shorter PFS and OS in lymphoma patients, as well as poor therapy response in acute leukemia." (PMID 41156312, 2025). "In addition, ABT‐199 (venetoclax) was tested, which is also a BH3‐mimetic drug that highly selectively inhibits Bcl‐2 and therefore effectively induces apoptosis in Bcl‐2 dependent lymphoma." (PMID 40405831, 2025). "Research has focused on the roles of MYC, BCL2, and Ki-67 proteins in lymphoma development." (PMID 40572636, 2025). "BCL2 is an anti-apoptotic, pro-survival protein that promotes lymphoma cell survival." (PMID 39558954, 2024). "Molecular subtype (GCB vs. ABC) and the presence of MYC and BCL2 or BCL6 rearrangements (as seen in double- or triple-hit lymphomas) also significantly affect outcomes, with double-hit lymphomas typically exhibiting more aggressive behavior and poorer survival rates." (PMID 39640090, 2024). "In addition, there is the term “dual or double expressor” lymphoma (DEL) that refers to MYC/BCL2 or MYC/BCL6 protein co-expression and triple expressor lymphoma (TEL) that refers to MYC/BCL2/BCL6 protein co-expression by IHC." (PMID 39038016, 2024). "In this study, targeted deep sequencing of 128 highly lymphoma-relevant genes was applied to identify pathogenic variants and CNVs in 26 patients with DLBCL-NOS involving the ocular adnexa and 2 patients with HGBCL with MYC and BCL2 rearrangements." (PMID 38542066, 2024). "It is well known that Bcl-2 and Mcl-1 are proteins that are overexpressed in lymphomas." (PMID 39769118, 2024). "However, if rearrangements are not found and only immunohistochemical (IHC) overexpression of MYC and BCL2 proteins is present, then the lymphoma is classified as double-expressor DLBCL (DEL)." (PMID 38397877, 2024).
lymphoma (continued). "High-grade DLBCL with MYC and BCL2 or BCL6 translocations are classified as DH/TH lymphomas." (PMID 38687198, 2024). "Of note, one of the 19 “double-hit” lymphoma cases showed rearrangements with all three FISH probes MYC, BCL2, and BCL6, which falls in the same diagnostic category as cases with MYC and BCL2 rearrangements only but has been called “triple-hit” lymphoma in the literature." (PMID 38903717, 2024). "This suggests that MYC and/or BCL2 overexpression may render lymphoma B cells more vulnerable to SpiD3 treatment." (PMID 38687198, 2024). "In this study, the BCL2 inhibitor venetoclax could repress lymphoma growth by interfering with the interaction between BCL2 and BIM." (PMID 38918775, 2024). "To establish whether computational simulations can accurately predict patient outcomes, we initially simulated the well-characterised subgroup of lymphoma patients with mutations affecting MYC and BCL2 (DH lymphoma)." (PMID 38965209, 2024). "Ig heavy chain VDJ region sequencing indicated that BCL2 + CK lymphomas are more clonal and less diverse based on Simpson clonality or Shannon diversity scores respectively, whereas BCL2 + C and BCL2 + K had an intermediate phenotype as compared to BCL2 lymphomas." (PMID 38570506, 2024). "Of note, among seven patients with BCL2 overexpression assessed by immunohistochemistry (IHC) of biopsy tissue, five (71.4%) patients achieved CR as best response, including one patient with triple-hit lymphoma." (PMID 38246951, 2024). "Notably, mouse lymphomas expressing BCL2 undergo drug-induced senescence, highlighting the potential significance of BCL2 in this process." (PMID 39595564, 2024). "Since venetoclax acts as an anti-tumor agent by competitively inhibiting the interaction between BCL-2 and proapoptotic proteins, it is very likely that this molecule affects lymphoma cells by regulating protein-protein interactions or protein functions, but not at the transcriptional level." (PMID 38918775, 2024). "Combination therapy targeting both MYC and BCL2 may provide a new strategy to improve the clinical outcome of MYC/BCL2 double-hit lymphomas and MYC/BCL2 dual expressers." (PMID 38918775, 2024). "It is however possible that combination activity is restricted to BCL2 positive lymphomas." (PMID 39284898, 2024). "In addition, DLBCL patients with a dual rearrangement of MYC and BCL2, “double/triple-hit” lymphoma, were recognized as a high-grade category with a poor prognosis in the latest WHO and ICC classification." (PMID 38158444, 2024). "However, clinical trial data in B-cell lymphoma are limited, and the low efficacy of venetoclax as a single agent in DLBCL and other B-cell lymphomas suggests that lymphoma cells are mostly resistant to BCL2 inhibition alone." (PMID 38893249, 2024). "However, a 4–6 fold increase in expression of BCL2 and MYC is commonly observed in these genes when they are mutated in lymphoma patient samples." (PMID 38965209, 2024). "The altered expression of BCL2 and BECN1 correlates with lymphoma outcomes, but whether this is associated with dysregulated cross-talk between autophagy and apoptosis remains to be elucidated." (PMID 37566004, 2023). "Dual translocation of MYC and BCL2 in patients with DLBCL is termed “double-hit lymphoma” (DHL), and dual protein overexpression of MYC and BCL2 without underlying translocations is termed “double-expressor lymphoma” (DEL)." (PMID 36315313, 2023). "Bcl2 is a star protein that inhibits apoptosis, and targeting the PI3K/AKT/mTOR pathway causes downregulation of Bcl2 protein expression, ultimately leading to lymphoma cell death." (PMID 37822596, 2023). "The molecular characteristics of the MCD subtype and the ABC subtype, such as deletion of CDKN2A, BCL2 overexpression, activation of BCR and NF-κB signaling pathways, may be the cause and result of lymphoma losing homing ability." (PMID 38077394, 2023).
lymphoma (continued). "Conditional deletion of Crebpp or Kmt2d in mouse B cells results in GC hyperplasia and increases the incidence of GC lymphoma in BCL2-driven mouse models after iterative SRBC immunization, with a spectrum of histopathological features ranging from early FL to DLBCL." (PMID 38022603, 2023). "Among these, activated B-cell-like (ABC) subtype, double expressor lymphoma (DEL, double expression of the MYC and BCL2 oncogenes), and double- or triple-hit lymphomas (DH/THLs, genetic rearrangements of MYC and BCL2 and/or BCL6) have been proven to obtain adverse clinical outcomes." (PMID 37361573, 2023). "Lymphocytes with high BCL-2 expression could be reflecting the activation or a proliferative state of these cells, and in lymphoma BCL-2 expression is considered a potential marker of poor prognosis." (PMID 37046835, 2023). "Over-expression of BCL-2 greatly accelerates c-MYC driven lymphoma development in mice." (PMID 36342579, 2023). "It has been shown that higher grade lymphoma, especially FL3b, is different from lower grade FL in its cytogenetic and immunohistochemical profile such as BCL2, BCL6, MYC and IRF4, which may contribute to the development of a different TME." (PMID 37591873, 2023). "BCL-2 is highly expressed in nearly all follicular lymphomas and in 30% of aggressive, diffuse large B cell and mantle cell lymphomas and can potentially protect polyploid lymphoma cells from cell death." (PMID 36934096, 2023). "Two hundred and forty-three (25.6%) were BCL2/MYC double-expressor lymphoma." (PMID 37032379, 2023). "Members of the lymphoma apoptosis regulatory family are considered to be regulators of cell death, including Bcl-2, Bcl-xl, and MCL-1, acting as chemical inhibitors of the pro-apoptotic protein Bax, which inhibits the release of Bax and cytochrome c and exerts an anti-apoptotic effect." (PMID 36851415, 2023). "Venetoclax (ABT-199) is an FDA-approved medication that targets Bcl-2; it is the first-in-class Bcl-2 inhibitor that treats lymphoid cancers and has shown remarkable clinical activity against certain types of haematological malignancies such as chronic lymphocytic leukaemia." (PMID 37834104, 2023). "In our study, we have focused on transformation-associated DNA alterations observed in an important subset of B-NHL—‘double-hit’ lymphomas that harbor MYC rearrangements in addition to the BCL2 rearrangement characteristically observed in FL and which are highly aggressive and difficult to treat." (PMID 38049665, 2023). "DLBCL with rearrangements involving MYC and BCL2/BCL6, which upregulate MYC gene expression, are referred to as double hit or triple hit lymphomas, and are associated with inferior progression free survival and overall survival in patients receiving traditional R-CHOP therapy." (PMID 36818048, 2023). "Double-hit or Triple-hit lymphoma (DHL/THL) is a subset of high-grade B cell lymphoma harboring rearrangements of MYC and BCL2 and/or BCL6, and usually associate with aggressive profile, while current therapies tend to provide poor clinical outcomes and eventually relapsed." (PMID 36823603, 2023). "Abnormally increased expression of pro-survival BCL-2 proteins or decreased levels of the pro-apoptotic BCL-2 family members have been implicated in the development and therapy resistance of a variety of cancers, particularly leukaemias and lymphomas." (PMID 37567974, 2023). "According to the 2016 revised WHO classification for lymphoid neoplasms, the co-expression of C-MYC and BCL-2 without associated rearrangements defines an adverse prognostic marker named double-expressor (DE) lymphoma." (PMID 36975591, 2023). "In an allelic comparison, the BCL2-A allele was not linked to lymphoma susceptibility; however, in an overdominant inheritance model, there is a reduced effect (protective genotype) between the BCL2-CA and BCL2-CC + AA genotypes." (PMID 36831357, 2023).
lymphoma (continued). "Distorted germinal centers may show residual labeling with CD10 and bcl-6, with a variable number of bcl-2+ lymphoma cells colonizing follicles." (PMID 37958219, 2023). "It is pertinent to mention that defective PCD does not alone aid in developing tumorigenesis, as only 5% of mice overexpressing Bcl-2 over eighteen months developed lymphoma, rather only the PCD inhibition aids in tumor development, which allows cells to live that would normally die." (PMID 36830564, 2023). "EXOC4 does not currently have a clear role in lymphoma, but it may be involved by sensitising lymphoma cells to doxorubicin or affecting Bcl-2 transcription." (PMID 37756103, 2023). "Whole-genome sequencing of longitudinal tumor pairs representing transformation of follicular lymphoma to high-grade B cell lymphoma with MYC and BCL2 rearrangements (double-hit lymphoma) identified coding and noncoding genomic alterations acquired during lymphoma progression." (PMID 38049665, 2023). "BCL2 expression is one of the most influential alterations in DLBCL and is already prognostically significant, as DLBCL with MYC and BCL2/BCL6 mutations are termed double hit or triple hit lymphomas and are associated with a worse prognosis." (PMID 36818048, 2023). "Together, we report a synergistic drug combination based on the biological properties of lymphoma, which are ill-prepared for polyploidy and susceptible to combined PLK4 and BCL-2 inhibition to induce and eliminate polyploid cells with negligible toxicity in healthy animals." (PMID 36934096, 2023). "We also evaluated in the two cell lines the activation of STAT3 and NF-κB pathways by western blot and found that OPL241 line shows the strongest expression of phospho- and total p65, ph-STAT3, and BCL2, in agreement with the high histological grade of the original lymphomas." (PMID 36503430, 2022). "Furthermore, inhibition of PLK1 with BI6727 (volasertib) synergized with the BCL2 inhibitor ABT199 (venetoclax) to kill MYC/BCL2 double‐hit lymphoma cell lines." (PMID 36214609, 2022). "These Hodgkin cells may also express markers of the associated lymphoma such as BCL2/BCL6 for follicular lymphoma and Cyclin D1 for mantle cell lymphoma, which may be combined with BCL2/BCL6 and CCND1 rearrangements in both contingents, respectively." (PMID 36428786, 2022). "Patients with co-expression of MYC and BCL2 but without underlying rearrangement, as defined by immunohistochemistry (IHC), are commonly referred to as double-expressor (DE) lymphoma." (PMID 35198451, 2022). "Similarly, MEK1/2 and proteasome inhibitors prevent phosphorylation and following UPS-mediated degradation of Bim, thereby synergistically interacting with Bcl-2 inhibitors in hematologic malignancies (e.g., MM and lymphoma)." (PMID 35574302, 2022). "Moreover, the expression of Bcl-2 transcripts in a feline lymphoma cell line (FT-1) was induced by some antineoplastic drugs, such as doxorubicin and prednisolone." (PMID 35448666, 2022). "As for previously reported BCL2 deregulation models, the development of lymphoma in such mice will thus need on-purpose breeding with mouse strains carrying the same types of second hits seen in human GC lymphomas." (PMID 36358756, 2022). "Mice transplanted with these cells rapidly develop lymphomas expressing high BCL-2 and MYC." (PMID 35961968, 2022). "Thus, we propose a therapeutic strategy in lymphoma that combines PRMT5 with MSI2 or BCL-2 inhibition." (PMID 36167829, 2022). "BCL2 and IRF4 were significantly more expressed in OPN-deficient than -competent Faslpr/lpr CD19 + cells, further supporting the histopathological assessment of high-grade ABC-DLBCL lymphomas." (PMID 36503430, 2022). "Finally, IACS‐010759 and the BCL2 inhibitor venetoclax effectively cooperated against MYC/BCL2 double‐hit lymphoma in xenograft‐based preclinical models." (PMID 34632715, 2022).